FGFR2 (fibroblast growth factor receptor 2)
Diseases named in the same sentence as FGFR2 in open-access papers (continued):
Sharing a sentence is not in itself a finding about the gene and the disease.
breast carcinoma (continued). "Genome wide association studies have identified single nucleotide polymorphisms (SNP) within fibroblast growth factor receptor 2 (FGFR2) as one of the highest ranking risk alleles in terms of development of breast cancer." (PMID 24265722, 2013). "It is anticipated that these variants are involved in gene regulation as exemplified by breast cancer susceptibility-associated variant rs2981582 that is correlated with FGFR2 transcript levels in breast cancer and normal breast tissue." (PMID 23785296, 2013). "For SNP rs1219648 at 10q26/FGFR2, association was observed in our previous study, the Carolina Breast Cancer Study (CBCS), and the Women’s Health Initiative (WHI) study, but not in the Women’s Insights and Shared Experiences study." (PMID 23593120, 2013). "A mouse mammary tumor virus (MMTV) insertional mutagenesis screen for genes associated with mammary cancer also identified FGFR2 and FGF10." (PMID 23300950, 2013). "Numerous genome-wide association studies (GWAS) also have identified approximately fifty common genetic loci for breast cancer risk in low penetrance genes such as FGFR2, ESR1, LSP1, MAP3K1, RAD51L1 and TOX3." (PMID 22606018, 2012). "Prominent examples are genome-wide association studies which led to the identification of novel breast cancer risk factors such as polymorphisms in FGFR2, CCND1, TOX3, MAP3K1, LSP1, CDKN2A, and 2B." (PMID 23226154, 2012). "Recent genome-wide association studies revealed strong evidence for more than 18 common breast cancer susceptibility alleles including FGFR2, CCND1, TNRC9, MAP3K1, and LSP1." (PMID 23226154, 2012). "Six of the previously identified SNPs showed a statistically significant association with breast cancer risk: rs2981582 (FGFR2), rs3803662 (TNRC9), rs12443621 (TNRC9), rs889312 (MAP3K1), rs3817198 (LSP1) and rs2107425 (H19)." (PMID 22867275, 2012). "In conclusion, it is likely that the causative variants tagged by rs2981578 in intron 2 of the FGFR2 gene cause a higher breast cancer risk by influencing FGFR2 expression levels." (PMID 21767389, 2011). "Multiple SNPs in the FGFR2 locus were significantly associated with contralateral breast cancer, including rs1219648 (per allele rate ratio (RR) = 1.25, 95%CI = 1.08-1.45)." (PMID 22087758, 2011). "Despite the clear evidence of involvement of FGFR2 in breast cancer, and association of polymorphisms in FGFR2 with breast cancer, the mechanism by which these polymorphisms predispose to breast cancer remains uncertain." (PMID 21418638, 2011). "Allele-specific regulation of FGFR2 mRNA expression has been reported previously, but the molecular basis for the association of these variants with breast cancer has remained elusive to date." (PMID 21767389, 2011). "If this primarily involved the luminal epithelial component of the breast tissue as it does in mice, this would explain why the increased breast cancer risk conferred by FGFR2 intron 2 SNPs is mostly restricted to ER-positive tumors." (PMID 21767389, 2011). "Our results suggest that the increased breast cancer risk associated with SNP rs2981578 is due to increased FGFR2 signaling activity in stromal fibroblasts, possibly also involving paracrine FGF10 signaling." (PMID 21767389, 2011). "Single Nucleotide Polymorphisms (SNPs) in intron 2 of the Fibroblast Growth Factor Receptor Type 2 (FGFR2) gene, including rs2981582, contribute to multifactorial breast cancer susceptibility." (PMID 21418638, 2011). "More studies are required to understand how the low-penetrance breast cancer risk polymorphisms in FGFR2 act to confer this risk, and how this information can be used to improve breast cancer prevention or treatment." (PMID 21418638, 2011). "We observed nominally significant associations between CBC and SNPs in three regions previously associated with breast cancer, 10q26 (FGFR2), 8q24, and 2q35, all of which had been previously replicated in studies of UBC." (PMID 22087758, 2011).
breast carcinoma (continued). "Germline genetic variation in an LD region within intron 2 of FGFR2 has been associated with a modestly increased breast cancer risk." (PMID 21767389, 2011). "Using even the smaller of these priors, our Bayesian analysis of these data strongly supports that FGFR2 is associated with breast cancer." (PMID 21853025, 2011). "The major finding of the study is that only those loci known to be associated with breast cancer risk in the general population, including FGFR2 (rs2981575), modified BRCA2-associated risk in our high-risk population." (PMID 21060860, 2010). "Although FGFR2 (rs2981575) was the only locus to reach genome-wide statistical significance, novel loci, rs16917302 and rs10509168 were each associated with breast cancer risk." (PMID 21060860, 2010). "Allele-specific up-regulation of FGFR2 was associated with increasing susceptibility to breast cancer." (PMID 21152100, 2010). "FGFR2 rs2981575 had the strongest association with breast cancer risk (per allele HR = 1.28, 95% CI 1.18–1.39, )." (PMID 21060860, 2010). "FGFR2 is a member of the fibroblast growth factor receptor family, showed heterozygous mutation in FGFR2 in breast cancer, and recently showed that SNPs (rs2981582) in this gene associated with increased risk of breast cancer." (PMID 21152100, 2010). "Two intronic SNVs in FGFR2 have been reported to increase susceptibility to breast cancer by regulating the downstream gene expression level." (PMID 21108794, 2010). "GWAS using germ line DNA showed a significant association of SNP in the FGFR2 gene with breast cancer." (PMID 21059268, 2010). "Estimates of breast cancer association for loci (two confirmatory loci at FGFR2 and TOX3, and two novel loci with stage 1 and 2 combined of p<10−4) among BRCA2 mutation carriers in a two-staged genome-wide association study." (PMID 21060860, 2010). "Recently, two genome-wide association studies have identified some genetic variants in the FGFR2 gene that were highly associated with breast cancer." (PMID 19500394, 2009). "Genome-wide association studies (GWAS) have identified breast cancer susceptibility loci in or near genes such as FGFR2, TOX3 (formerly known as TNRC9), LSP1, HCN1/MRPS30, MAP3K1 and at 2q that had not previously been considered." (PMID 19232126, 2009). "The strongest associations have been found with polymorphisms in FGFR2; each copy of the T allele of rs2981582 was found to be associated with a 26% increased breast cancer risk." (PMID 19232126, 2009). "As FGFR2 had already been implicated in breast cancer, the significance of the FGFR2 SNPs as susceptibility alleles seemed evident." (PMID 19607694, 2009). "Polymorphisms in or near TOX3, LSP1, HCN1, MAP3K1 and at 2q35 are less strongly associated with breast cancer risk than polymorphisms in FGFR2; the increased risks range from 4% to 20% with each risk allele." (PMID 19232126, 2009). "Recent data showing a possible association between genetic alterations in the FGFR2 gene and risk of breast cancers raised the interest to studies aimed to better address this issue." (PMID 18575591, 2008). "The GWAS identified four SNPs (rs1219648, rs2420946, rs11200014 and rs2981579) in intron 2 of FGFR2, which showed significant association with breast cancer." (PMID 21655367, 2008). "Again, although FGFR2 is a plausible breast cancer gene, the functional significance of these common variants in FGFR2 loci is not clear." (PMID 21655367, 2008). "The discovery of association of SNPs in intron 2 of FGFR2, which encode fibroblast growth factor receptor 2, with breast cancer risk was also reported in two independent GWASs." (PMID 21655367, 2008). "SNPs in intron 2 of fibroblast growth factor receptor 2 (FGFR2) have emerged as top hits from multiple genome-wide association studies of breast cancer." (PMID 18681954, 2008).
breast carcinoma (continued). "Assuming the association between FGFR2 variants and breast cancer is mediated through breast density, one would expect to see a 33% difference in mammographic density comparing homozygous variants with homozygous wildtypes." (PMID 18681954, 2008). "For example, SNPs in TOX3 and CASP8 alter the risk for developing breast cancer, and SNPs in FGFR2 and TOX3 are strongly associated with ER-positive breast cancer." (PMID 19094228, 2008). "In an attempt to address this issue, we analysed the combined effects of SNP rs2981582 in FGFR2 and each one of the other six SNPS on breast cancer risk in our ORIGO cohort." (PMID 17997823, 2007). "To investigate the combined effects of these SNPs on breast cancer risk, we calculated the odds ratios of the combination of the most important SNP (rs2981582 in FGFR2) with one other SNP." (PMID 17997823, 2007). "In the BCAC study, SNP rs2981582 in FGFR2 was most strongly associated with breast cancer, an association that was replicated in three independent postmenopausal breast cancer cohorts." (PMID 17997823, 2007). "We also noted a correlation between the number of minor alleles of rs2981582 in FGFR2 and the average number of first-degree and second-degree relatives with breast cancer and/or ovarian cancer (P = 0.05)." (PMID 17997823, 2007). "Additionally, recent findings highlight subtype-specific expression of FGFR2 splice variants in breast cancer." (PMID 41584352, 2026). "Because of the inconsistent association between this gene polymorphism in different ethnic groups, our study aimed to evaluate and clarify the relationship between breast cancer susceptibility and FGFR2 polymorphism(rs2981578)using a matched case-control study design in Gondar, Northwest Ethiopia." (PMID 40748883, 2025). "Additionally, FGF7 and its receptor fibroblast growth factor receptor-2 (FGFR2), along with its various isoforms, are significantly linked to the progression risk in breast cancer cell lines." (PMID 40140925, 2025). "FGFR2 rs2981578 G/A genotype association in breast cancer patients vs. controls." (PMID 40748883, 2025). "Hinting at the possibility that the FGFR2 rs2981578 polymorphism may heighten FGFR2’s transcriptional activity or expression as breast cancer advances, underscoring the potential prognostic value of this genetic variation in breast cancer prognosis." (PMID 40748883, 2025). "Moderate penetrance genes have 20–50% lifetime breast cancer risk.In addition, 80 common low penetrance genes including, FGFR2 were identified by genome-wide association studies (GWAS), and smaller studies were also explained as having a 20% lifetime risk of breast cancer." (PMID 40748883, 2025). "The activation of the FGF7/FGFR2 axis may cause the degradation of the ER and thus prevent tamoxifen from inhibiting ER+ breast cancer." (PMID 39596875, 2024). "Fibroblast growth factor receptor 2 (FGFR2) has been associated with breast cancer." (PMID 39596875, 2024). "However, nuclear FGFR2 is often associated with increased tumor size and lower overall survival rates in various types of breast cancer." (PMID 39404930, 2024). "Additionally, one GWAS presented solid evidence of a strong association between the FGFR2 locus and ER status in breast cancer patients." (PMID 38166892, 2024). "Our study investigated in silico the associations between FGFR2 expression in breast cancer subtypes using publicly available TCGA data, and further interrogated the FGFR2 exon 8 and exon 9 expression levels, as proxies of the FGFR2 IIIb and IIIc isoforms, in clinical subtypes." (PMID 39596875, 2024). "A higher FGFR2 mRNA was significantly associated with luminal, oestrogen receptor (ER)-positive breast cancers, and invasive lobular carcinomas, whereas a lower FGFR2 was associated with human epidermal growth factor receptor 2 (HER2)-positive breast cancer and invasive ductal carcinomas." (PMID 39596875, 2024).
breast carcinoma (continued). "In the COSMIC database, the frequency of the FGFR2 Y375C mutation in breast cancer was 0.01%." (PMID 37980453, 2023). "Specifically, FGFR2 gene amplification has been implicated in gastric and breast cancer." (PMID 36985681, 2023). "In addition, gene polymorphisms of FGFR2, including rs2981582,226, 227, 228, 229 rs1219648,230, 231 rs35054928, and rs45631563,232 have been found to be associated with susceptibility to breast cancer." (PMID 37750089, 2023). "Furthermore, several case–control studies were conducted in Mexican, West Siberian, South American, Chinese, Iranian, Australian Caucasian, and Jordanian Arab women to determine the correlation between FGFR2 gene polymorphisms and breast cancer vulnerability." (PMID 37107577, 2023). "This study confirms the association of FGFR2 polymorphisms with breast cancer risk." (PMID 37107577, 2023). "Therefore, the FGFR2 gene has been identified as a potential risk factor for breast cancer development due to the genetic variations in this gene." (PMID 37107577, 2023). "Many previous studies have identified Fgfr2 as an oncogene for breast cancer 35, 36, yet its role in BRCA1-associated breast cancer remains unclear." (PMID 37063417, 2023). "Several studies reported the association between mutations affecting FGFR2 and breast cancer." (PMID 35176995, 2022). "Master regulators of FGFR2 signalling and breast cancer risk." (PMID 35563727, 2022). "Interestingly, BRCA-1- and ER-double-positive breast cancers showed not only increased expression of FGFR2 but also the presence of the SNP rs2981582, which is associated with high risk of breast cancer." (PMID 35193394, 2022). "A point mutation in FGFR2 has been detected in breast cancer cells." (PMID 36601474, 2022). "Thus, the position of these mutations on the protein affects the function of FGFR2 in breast cancer, suggesting that multiple regulatory mechanisms for FGFR2 signalling are present in vivo." (PMID 35193394, 2022). "Based on FGFR2 interaction with other genetic and environmental factors, FGFR2 may contribute to polygenic risk scoring in breast cancer family history clinics." (PMID 35193394, 2022). "Apart from breast cancer, 10–12% of endometrial carcinoma and 4–5% of NSCLCs bear FGFR2 mutations." (PMID 35494629, 2022). "In contrast, increased FGFR2 activity is found in several other cancers, including activating mutations in endometrial, lung, and gastric cancer, and amplifications and overexpression of FGFR2 in gastric and breast cancer." (PMID 35887382, 2022). "Indeed, the frequency of FGFR2 mutations or translocations in the TCGA breast cancer dataset was approximately 2% of patients." (PMID 34344433, 2021). "SNPs in the FGFR2 gene are also associated with increased risk of breast cancer." (PMID 34068954, 2021). "At the gene level, only FGFR2 was significantly associated with breast cancer." (PMID 33735170, 2021). "It has been discussed that nuclear localisation of FGFR2 in breast cancer cells may be associated with a more differentiated phenotype." (PMID 32522271, 2020). "Our group has published two breast cancer GWAS: The first reported association of chromosome 10q26 (FGFR2) and 16q12 (TOX-LOC643714) to breast cancer while the second showed association of 3q25.1 (SIAH2) with hormonal-positive breast cancer in the Japanese population." (PMID 31757997, 2019). "Our study indicates that the A allele of P21 and the allele T of FGFR2 may be associated with an increased risk of early-onset of breast cancer in Yogyakarta, Indonesia." (PMID 31759353, 2019). "Among them, 28 SNPs are known to be associated with overall breast cancer risk including 3 SNPs already identified to be associated with breast cancer risk in the Tunisian population namely rs1219648, rs2981582 in FGFR2 and rs8051542 in TOX3." (PMID 30594178, 2018). "Furthermore, FOXA1, GATA3, ESR1 and SPDEF are reported as master regulators in FGFR2 signaling and breast cancer risk in ER+ cells." (PMID 29741575, 2018).
breast carcinoma (continued). "In addition, the association between variants in FGFR2 and ER status in breast cancer was stronger among patients with HER2− tumors." (PMID 27764800, 2016). "In addition, these TFs are the master regulators (MRs) of the FGFR2 response, which is strongly associated with risk of breast cancer development." (PMID 27997592, 2016). "The FGFR2 locus is known to be associated with breast cancer risk." (PMID 27764800, 2016). "The first breast cancer risk variants identified in the GWAS era were in the FGFR2 locus." (PMID 27764800, 2016). "FGFR2 has been implicated in development and progression of breast cancer (BCa)." (PMID 27476168, 2016). "Moreover, the GA and AA genotypes of FGFR2 rs2981582 appear to be associated with lower mammographic density and reduced breast cancer risk." (PMID 26911390, 2016). "The role of FGFR2 in breast cancer risk may therefore be distinct from the role normally associated with FGFRs in tumour progression." (PMID 27236187, 2016). "Variants in the FGFR2 locus were the first identified via GWAS with respect to breast cancer risk." (PMID 27764800, 2016). "In conclusion, our analysis of FGFR2 signalling and the effect of breast cancer risk variants suggest that the role of FGFR2 germline variants in breast cancer risk may be linked to reducing a cell’s ability to respond to oestrogen activation." (PMID 27236187, 2016). "In this high-powered GWAS performed in a case-cohort of breast cancer patients with detailed clinical data, further information with respect to variants in the FGFR2 locus and their influence on breast cancer were provided, particularly regarding tumor ER status." (PMID 27764800, 2016). "GWAS have identified variation in the FGFR2 locus as risk factors for breast cancer." (PMID 26421298, 2015). "It is unlikely that the association between FGFR2 SNPs and subtypes of breast cancers differed by whether corresponding information were available." (PMID 26421298, 2015). "Further, more studies have strongly suggested that FGFR2 is a breast cancer susceptibility gene." (PMID 26431494, 2015). "FGFR2 has been identified as a breast cancer susceptibility gene." (PMID 26431494, 2015). "Similarly, fibroblast growth factors play a role in promoting proliferation and differentiation of cells, and mediating angiogenesis, and FGFR2 has been consistently found to be associated with breast cancer." (PMID 26431041, 2015). "In addition, single point mutations in the FGFR2 gene are associated with increased risk in human breast cancer." (PMID 25079073, 2014). "Moreover, Fgfr2 upregulation as a result of allelic polymorphism has been associated with human breast cancer, suggesting a causal role of excessive Fgfr2 activities in the disease." (PMID 24718286, 2014). "Our results suggest that intron 2 SNPs of FGFR2 may contribute to genetic susceptibility of breast cancer in North India population." (PMID 25333473, 2014). "Genome-Wide Association Studies (GWAS) have identified Fibroblast growth factor receptor 2 (FGFR2) as a candidate gene for breast cancer with single nucleotide polymorphisms (SNPs) located in intron 2 region as the susceptibility loci strongly associated with the risk." (PMID 25333473, 2014). "Moreover, restriction of the risk conferred by FGFR2 variants to ER-positive and PR-positive tumors suggests that these SNPs affect the reproductive hormone-related pathway in the development of breast cancer in North Indian women." (PMID 25333473, 2014). "In our study we examined the immunoglobulin-like domains D2 and D3, the transmembrane domain and the tyrosine kinase domain of FGFR2, i.e. regions in which the typical mutational hot spots of craniosynostosis syndromes are located, in somatic tumor tissue of sporadic breast cancer patients." (PMID 23527311, 2013). "FGFR2 alternative splicing is highly relevant as polymorphism in intron 2, which may lead to increased expression, is associated with higher risk of breast cancer." (PMID 23758675, 2013).